SNRPF (small nuclear ribonucleoprotein polypeptide F)
Description:
Plays a role in pre-mRNA splicing as a core component of the spliceosomal U1, U2, U4 and U5 small nuclear ribonucleoproteins (snRNPs), the building blocks of the spliceosome. Component of both the pre-catalytic spliceosome B complex and activated spliceosome C complexes. As a component of the minor spliceosome, involved in the splicing of U12-type introns in pre-mRNAs. As part of the U7 snRNP it is involved in histone 3'-end processing.
Synonyms: snRNP-F; Sm-F; SmF
Tractability: Small molecule: a structure with a bound ligand is known. PROTAC: ubiquitination databases record sites on it; its protein half-life has been measured.
Gene: Protein-coding gene on chromosome 12 (95,858,931 to 95,903,828, forward strand). Ensembl gene ENSG00000139343.
Subcellular location: Cytoplasm, cytosol; Nucleus
Pathways (Reactome):
Metabolism of RNA: SLBP Dependent Processing of Replication-Dependent Histone Pre-mRNAs; SLBP independent Processing of Histone Pre-mRNAs; mRNA Polyadenylation; mRNA Splicing - Major Pathway; mRNA Splicing - Minor Pathway; snRNP Assembly
Disease: Dengue Virus-Host Interactions; SARS-CoV-2 modulates host translation machinery
Chromatin organization: CHD1 and CHD2 subfamily
Gene expression (Transcription): RNA Polymerase II Transcription Termination
Gene Ontology:
Molecular function: protein binding; RNA binding
Biological process: mRNA splicing, via spliceosome; RNA splicing; spliceosomal snRNP assembly; 7-methylguanosine cap hypermethylation; negative regulation of mRNA splicing, via spliceosome; nuclear histone mRNA catabolic process; spliceosomal complex assembly; spliceosomal tri-snRNP complex assembly; spliceosome conformational change to release U4 (or U4atac) and U1 (or U11); U2-type prespliceosome assembly; protein-RNA complex assembly
Cellular component: catalytic step 2 spliceosome; cytosol; methylosome; nucleus; pICln-Sm protein complex; post-mRNA release spliceosomal complex; post-spliceosomal complex; precatalytic spliceosome; small nuclear ribonucleoprotein complex; SMN-Sm protein complex; spliceosomal complex; U1 snRNP; U11/U12 snRNP; U12-type catalytic step 2 spliceosome; U12-type precatalytic spliceosome; U12-type spliceosomal complex; U2-type catalytic step 1 spliceosome; U2-type catalytic step 2 spliceosome; U2-type precatalytic spliceosome; U2-type spliceosomal complex; U4 snRNP; U4/U6 x U5 tri-snRNP complex; U7 snRNP; nucleoplasm; U2 snRNP; and 5 more
Genetic constraint (gnomAD): Loss-of-function variants: 1 observed, 3.98 expected, observed/expected ratio (o/e) 0.25, 90% interval 0.088 to 1.17. That is too few expected variants to judge how well the gene tolerates losing a copy. Missense variants: 11 observed, 28.22 expected, observed/expected ratio (o/e) 0.39, 90% interval 0.24 to 0.64. Synonymous variants: 7 observed, 8.98 expected, observed/expected ratio (o/e) 0.78, 90% interval 0.44 to 1.45.
Homologues: Orthologues: guinea pig SNRPF (100% identical), mouse Snrpf (100% identical), pig SNRPF (100% identical), rabbit SNRPF (100% identical), rat Snrpf (100% identical), tropical clawed frog snrpf (100% identical), zebrafish snrpf (98% identical), Drosophila melanogaster SmF (77% identical), Caenorhabditis elegans snr-5 (65% identical). Paralogues in human: LSM6 (44% identical).
Diseases named in the same sentence as SNRPF in open-access papers:
SNRPF is named in the same sentence as 13 diseases in open-access papers, as found by Europe PMC text mining. Sharing a sentence is not in itself a finding about the gene and the disease. The quoted sentences say what the papers report.
glioma (2 papers, 2017 to 2021). A benign or malignant brain and spinal cord tumor that arises from glial cells (astrocytes, oligodendrocytes, ependymal cells). "In vitro experiments have revealed that ubiquitin carboxy-terminal hydrolase isozyme L5 could inhibit human glioma cell migration and invasion by downregulating SNRPF." (PMID 35126467, 2021). "Our study showed that UCH-L5 could inhibit migration and invasion of glioma cells via down regulating expression of SNRPF." (PMID 29371935, 2017). "Furthermore, we discovered that UCH-L5 could inhibit cell migration and invasion of glioma cell lines through downregulating SNRPF, a factor of Sm protein ring in the spliceosome." (PMID 29371935, 2017). "According to the abnormal protein level in high and low degree glioma, and mass spectra (MS) result after UCH-L5 overexpression, SNRPF, SNRPN and CKLF were as potential target genes of UCH-L5." (PMID 29371935, 2017). "It has been reported that the expression of SNRPN, SNRPF, and CKLF was abnormal in gliomas or other tumors." (PMID 29371935, 2017). "It has been reported that expression of SNRPN, SNRPF and CKLF is abnormal in glioma tissues." (PMID 29371935, 2017).
laryngeal squamous cell carcinoma (2 papers, 2022 to 2023). A squamous cell carcinoma that arises from the larynx. "SNRPD2 and SNRPF are the core proteins related to below-background radiation, and further affect the proliferation of well-differentiated laryngeal squamous cell carcinoma cells." (PMID 36371223, 2022). "SNRPF dysregulation has been reported in some cancers, including colorectal, laryngeal squamous cell carcinoma cells and renal cell carcinoma, but not in lung cancer." (PMID 37185598, 2023).
autism spectrum disorder (1 paper, 2024). A spectrum of developmental disorders that includes autism, and Asperger syndrome. "For example, the SNRPF gene is involved in RNA processing and splicing functions and has been associated with circadian rhythm and autism spectrum disorder in humans." (PMID 39202342, 2024).
colon cancer (1 paper, 2022). "Our findings indicated that DEDD2, GTF2H5, SNRPA1, BICD1, CELF1, and CLK3 were prognostic risk factors for colon cancer, while ADAD1, CMTR1, HNRNPUL1, FTSJ3, WDR43, THUMPD3, SNRPF were prognostic protective factors." (PMID 36212157, 2022).
gallbladder cancer (1 paper, 2024). "A comparative analysis of differential proteomic data revealed 7 hypermethylated or down-regulated genes (e.g., FBN1, LPP, SOD3) and 61 hypomethylated or up-regulated genes (e.g., HBE1, SNRPF, TPD52), which contributed to the early diagnosis of gallbladder cancer." (PMID 38427106, 2024).
lung squamous cell carcinoma (1 paper, 2023). "Moreover, NEDD9, MRPL21, SNRPF, and SCLT1 genes were identified to be involved in lung squamous cell carcinoma drug sensitivity/resistance." (PMID 37185598, 2023).
neuroblastoma (1 paper, 2024). Neuroblastoma (NB) is the most common solid, extracranial childhood tumor. "We found that SNRPD3, SNRPF and LSM4 had the strongest independent prognostic effect on neuroblastoma patient outcome among the core spliceosome assembly genes as measured by hazard ratios for event-free (EFS) and overall (OS) patient survival." (PMID 38049564, 2024).
cancer (6 papers, 2013 to 2023). A tumor composed of atypical neoplastic, often pleomorphic cells that invade other tissues. "Among the 16 candidate cancer genes that encoded transcription factors, 13 were known to be tumorigenic and three were novel: CDK1, SNRPF, and ILF2." (PMID 23799036, 2013). "In other words, dysregulation of SNRPF may potentially influence the development and progress of cancer by generating different isoforms from the pre-matured mRNAs in an alternative splicing way29,30." (PMID 36535956, 2022). "Interestingly, the analysis revealed that 7 targets (SF3B1, SF3B3, SNRPA, SNRPE, SNRPF, HNRNPA3 and EFTUD2) are physically interacting proteins within the spliceosome complex, suggesting that JA might regulate the cancer spliceosome to induce tumor-specific cell death." (PMID 28198434, 2017).
tumor (5 papers, 2017 to 2026). "SNRPD3 and U2AF2 showed (50%) the highest association; DDX5, DDX17, and SNRPF in between (40–50%) with neoplasm class." (PMID 34918006, 2022). "Antisense oligonucleotide-mediated inhibition of SNRPF disrupts this feedback loop, downregulates DDX24 and E2F4 via IR, and significantly impairs tumor growth in vitro, in vivo, and in patient-derived xenografts." (PMID 42107058, 2026).
SNRPF also shares sentences with these, for which no sentence is quoted: endometrial cancer (1 paper); gastric cancer (1); prostate carcinoma (1); renal cell carcinoma (1).